MIAT (myocardial infarction associated transcript)
Diseases named in the same sentence as MIAT in open-access papers (continued):
Sharing a sentence is not in itself a finding about the gene and the disease.
schizophrenia (16 papers, 2017 to 2024). A major psychotic disorder characterized by abnormalities in the perception or expression of reality. "More specifically, genetic variants of the lncRNA MIAT (also termed Gomafu) have been associated with paranoid schizophrenia in the Han Chinese population." (PMID 27913161, 2017). "Initial investigations into its role in schizophrenia reported lower levels of the MIAT transcript in the STG in subjects with schizophrenia compared to controls." (PMID 29657307, 2018). "The MIAT gene is located on chromosome 22q12.1, in close proximity to the chromosome 22q11.2 schizophrenia candidate region." (PMID 29657307, 2018). "Within the CNS, MIAT is reported to be expressed in neuronal populations in which the mature transcript is localised to the nucleus and mediates its activity by binding to the splicing factors, SF1, QKI, SRSF1, and CELF, supporting a role for MIAT in regulating alternative splicing in schizophrenia." (PMID 29657307, 2018). "Furthermore, increased MIAT significantly decreased DISC1 (disrupted in schizophrenia 1), ERBB4 (v-erb-a erythroblastic leukemia viral oncogene homolog 4) and their alternatively spliced variants in SZ patient brains." (PMID 29534728, 2018). "Thus, the reported loss of MIAT transcript in schizophrenia may regulate the changes in DISC1 and ERBB4 splice variation seen in subjects with schizophrenia." (PMID 29657307, 2018). "MIAT, NEAT1, and MALAT1 are coordinately changed in schizophrenia." (PMID 36412908, 2022).
infarction (15 papers, 2016 to 2025). A localised pathological necrosis of tissue resulting from obstruction of the blood supply usually by a thrombus, an embolus, or vascular torsion. "AK028326 (also known as RNCR2 or Gomafu), generally called myocardial infarction associated transcript (Miat), was described as a pro-fibrotic and pro-apoptotic lncRNA following myocardial ischemia." (PMID 34697716, 2022). "This study aimed to reveal the biological roles of lncRNA myocardial infarction associated transcript (MIAT) in oxidized low-density lipoprotein (ox-LDL)-induced human vascular smooth muscle cells (VSMCs)." (PMID 34016053, 2021). "GOMAFU (also known as MIAT, myocardial infarction associated transcript) is a lncRNA expressed in the nucleus of dividing NSCs and differentiating neurons." (PMID 32344798, 2020). "Several lncRNAs with a GC-AG intron were described to play a role in neuron development and growth like the MEG3 gene, the NEAT1 gene, the SOX2-OT gene, the GDNF-AS1 (GDNF antisense RNA 1) gene and the MIAT (myocardial infarction associated transcript)." (PMID 32499820, 2020). "Myocardial infarction-associated transcript (MIAT), also known as Gomafu or retinal noncoding RNA 2 (RNCR2), was first identified as a susceptibility locus for myocardial infarction patients and is reportedly highly expressed in retinal precursor cells." (PMID 27043545, 2016). "Gomafu, also known as MIAT (Myocardial infarction associated transcript), is found to interact with psychiatric disorders through lncRNA–miRNA interactions, and it has been found that reduced levels of Gomafu expression can be seen in the brains of postmortem schizophrenic patients." (PMID 39456775, 2024).
diabetic cardiomyopathy (12 papers, 2017 to 2025). Diabetic cardiomyopathy is a disorder of the heart muscle in people with diabetes. "In diabetic cardiomyopathy, high glucose induces the expression of myocardial infarction-associated transcript (MIAT) and upregulates the death-associated protein kinase 2 (DAPK2) expression by sponging miR-22-3p, which consequently leads to cardiomyocyte apoptosis." (PMID 35990951, 2022). "In a rat model of diabetic cardiomyopathy, MIAT and circMAP3K5 upregulate DAPK2 expression through competitive binding to miR-22-3p, which in turn promotes cardiomyocyte apoptosis." (PMID 40630623, 2025). "In diabetic cardiomyopathy (DCM), lncRNA myocardial infarction associated transcript (MIAT) was significantly upregulated in the rat model of DCM." (PMID 34422899, 2021). "For example, MIAT serves as a ceRNA to increase DAPK2 through sponging miR‐22‐3p in diabetic cardiomyopathy." (PMID 33009725, 2020). "Previous studies demonstrated that MIAT was highly expressed in cardiomyocytes, and involved in MI, diabetic cardiomyopathy, ischemic stroke, angiogenesis." (PMID 29487526, 2018). "In our previous studies, several ncRNAs including MIAT, MALAT1, H19 and circHIPK3 have been suggested to participate in the modulation of cardiomyocyte apoptosis and autophagy and consequently result in the development of diabetic cardiomyopathy." (PMID 31240820, 2019). "Another study showed that lncRNA MIAT could function as an opposing endogenous RNA to increase DAPK2 levels by sponging miR‐22‐3p, ultimately resulting in the apoptosis of cardiomyocytes, a critical process involved in the development of diabetic cardiomyopathy." (PMID 39971705, 2025).
ischemic stroke (11 papers, 2018 to 2024). A stroke disorder caused by obstruction of blood flow to the brain, due to thrombotic (local blood clot formation) or embolic (due to a blood clot or other material traveling from another site) event. "In ischemic stroke patients, MIAT expression was significantly upregulated, and MIAT was a prognostic marker of prognosis in patients with IS." (PMID 31237148, 2019). "Moreover, lncRNA MIAT is considered an unfavorable biomarker in ischemic stroke and response to therapeutics, in which lower levels of MIAT were reported in patients with promising outcomes." (PMID 39021183, 2024). "(2021c) showed that the expression level of MIAT in serum of patients with ischemic stroke was higher than that of normal people, and down-regulation of MIAT could reduce neurological damage and brain tissue damage in MCAO/R mice." (PMID 36275741, 2022). "Additionally, ischemic stroke patients with increased MIAT expression had a relatively poor prognosis compared to a group with low MIAT expression." (PMID 30967760, 2019). "Moreover, the lncRNA myocardial-infarction associated transcript (MIAT) is highly expressed in human carotid plaques and may act as a diagnostic marker in ischemic stroke." (PMID 37259293, 2023). "Recent studies have identified several lncRNAs that modulate autophagy in ischemic stroke, including MALAT1, MIAT, SNHG12, H19, AC136007." (PMID 39021183, 2024). "They found that the lncRNA MIAT and regulated in development and DNA damage response 1 (REDD1) expressions were upregulated in both the cellular model and rat model of ischemic stroke." (PMID 39021183, 2024).
lung cancer (11 papers, 2017 to 2023). A malignant neoplasm involving the lung. "In particular, increased MIAT expression was associated with advanced stages and shorter OS times of lung cancer patients." (PMID 30967527, 2019). "We investigated the expression of MIAT in lung cancer tissues, and the association between MIAT and prognosis of lung cancer patients." (PMID 29487526, 2018). "Clinical association between MIAT expression and clinicopathological variables in lung cancer patients." (PMID 29487526, 2018). "However, the role of MIAT on acquired resistance in lung cancer and the underlying mechanisms remain unclear." (PMID 29487526, 2018). "MIAT, a recently identified oncogenic lncRNA, has been reported to be upregulated in several types of cancers, including papillary thyroid cancer, lung cancer and acute myeloid leukemia." (PMID 33154765, 2020). "Our previous studies show that MIAT expression is upregulated in lung cancer tissues compared with adjacent tissues." (PMID 30967527, 2019). "Here, we showed that the expression of MIAT in lung cancer tissues was upregulated compared with adjacent tissues." (PMID 29487526, 2018). "Taken together, our findings demonstrated that knockdown of MIAT by siRNA enhances lung cancer cells to gefitinib through the PI3K/Akt signaling pathway by epigenetically regulating miR-34a." (PMID 29487526, 2018). "Because treatment failure and the poor prognosis of lung cancer are due to high metastasis and invasion, we further identified the biological role of MIAT in tumor progression." (PMID 29228680, 2017). "MIAT can target the miR-149-5p/FOXM1 axis to regulate lung cancer progression partially." (PMID 38095636, 2023). "Thus, we concluded that the expression of MIAT can be used to predict the outcome of patients with lung cancer." (PMID 29487526, 2018). "It has been reported that MIAT levels could be upregulated in high glucose conditions and in lung cancer, and NTT expressions might be found in processes involving T cell activation." (PMID 30119681, 2018). "In this study, we found that lncRNA MIAT was upregulated in lung cancer tissues compared with adjacent tissues, and the patients with low lncRNA MIAT had longer overall survival time and progression-free survival time than patients with high lncRNA MIAT expression." (PMID 29487526, 2018). "In addition, qRT-PCR performed in human lung cancer tissues with high (n = 5) or low (n = 5) MIAT expression showed that miR-34a expression is negatively correlated with MIAT expression." (PMID 29487526, 2018). "Our findings demonstrate that silencing of MIAT sensitizes lung cancer cells to gefitinib by epigenetically miR-34a, and MIAT may be a useful prognostic marker and therapeutic target for lung cancer patients." (PMID 29487526, 2018). "And knockdown of MIAT by siRNA could sensitize lung cancer cells to gefitinib." (PMID 29487526, 2018). "However, whether MIAT plays a role on drug resistance in lung cancer remain unknown." (PMID 29487526, 2018). "Thus, MIAT may be a useful prognostic marker and therapeutic target for lung cancer patients." (PMID 29487526, 2018). "In the NSCLC cohort, we observed that MIAT was upregulated in lung cancer tissues compared with the non-tumor tissues." (PMID 29228680, 2017).
colorectal cancer (9 papers, 2018 to 2023). A primary or metastatic malignant neoplasm that affects the colon or rectum. "For example, MIAT promotes the proliferation and metastasis of colorectal cancer cells via miR-132/Derlin-1 pathway." (PMID 36934152, 2023). "For example, in colorectal cancer cells, MIAT bound to miR-132, a tumor suppressor in colorectal cancer, led to downregulation of miR-132 and facilitate proliferation and metastasis of cancer cells." (PMID 31372094, 2019). "A recent study on colorectal cancer and MIAT showed that MIAT promoted the growth and metastasis of colorectal cancer cells by regulating the Mir-132/Derlin-1 pathway, indicating the ceRNA relationship between MIAT and Mir-132, which proved that MIAT played the role of ceRNA in Mir-132." (PMID 34108986, 2021). "Upregulation of MIAT was found both in colorectal cancer tissues and cell lines." (PMID 32274858, 2020). "Many studies revealed that MIAT has been demonstrated as a key switcher in regulation of various biological and pathological processes in human cancers including non-small-cell lung cancer, neuroendocrine prostate cancer, and colorectal cancer." (PMID 31886187, 2019). "However, the role and mechanism of MIAT in colorectal cancer (CRC) have not been investigated." (PMID 29686537, 2018).
non-small cell lung carcinoma (9 papers, 2018 to 2024). A group of at least three distinct histological types of lung cancer, including non-small cell squamous cell carcinoma, adenocarcinoma, and large cell carcinoma. "Recent studies have identified the oncogenic role of MIAT in several types of cancers such as papillary thyroid cancer and non-small cell lung cancer." (PMID 33551826, 2020). "In non-small-cell lung cancer cell line, knockdown of MIAT resulted in decreased ZEB1 expression, indicating cis-action of MIAT on regulating ZEB1." (PMID 30119681, 2018). "In addition, the MIAT/miR-150-5p/ZEB1 signaling pathway plays an oncogenic role in non-small cell lung cancer." (PMID 34811354, 2021).
glioblastoma (8 papers, 2017 to 2024). The most malignant astrocytic tumor (WHO grade IV). "Beyond its role in cardiovascular diseases, MIAT dysregulation has been associated with a variety of disorders, such as impaired neuronal function and glioblastoma and various fibrosis diseases." (PMID 39379100, 2024). "MIAT (Myocardial Infarction Associated Transcript) has recently been found to possess tumor‐promoting properties in glioblastoma and NB, which is contrary to our findings and need further investigation." (PMID 32216054, 2020). "Although hypoxia-response genes such as MIAT might be the target genes of ALKBH1-related m6A modification in glioblastoma, the profiling of m6A and the underlying mechanism of MIAT regulation by m6A during AS development is unknown." (PMID 31797919, 2019). "Recent studies confirmed that MIAT knockout eradicated the extended migration and survival of neuroblastoma and glioblastoma cell lines and increased the apoptosis of basal cells." (PMID 34108986, 2021). "The lncRNA myocardial infarction-associated transcript (MIAT), as a hypoxia-response gene, was reported as a target gene of ALKBH1-modulated m6A in glioblastoma." (PMID 31797919, 2019). "We applied the classification criterion to describe the expression of PVT1, CYTOR, HAR1A and MIAT in glioblastoma subtypes." (PMID 29108264, 2017). "The results implied that CYTOR and MIAT may be associated with amplification of PDGFRA and IDH1 mutations, HAR1A may be related with neuron markers in glioblastomas." (PMID 29108264, 2017). "Up-regulation of a number of oncogenic lncRNAs such as H19, MALAT1, SNHGs, MIAT, UCA, HIF1A-AS2 and XIST in addition to down-regulation of other tumor suppressor lncRNAs namely GAS5, RNCR3 and NBAT1 indicate the role of these lncRNAs in the pathogenesis of glioblastoma." (PMID 33634032, 2020).
melanoma (8 papers, 2019 to 2024). A malignant, usually aggressive tumor composed of atypical, neoplastic melanocytes. "MIAT was overexpressed in melanoma tissue samples, and enforced MIAT expression significantly promoted the oncogenic activities of cancer cells through the PI3K/AKT signaling pathway." (PMID 32274858, 2020). "For example, the lncRNA MIAT binds to TCF12 and facilitates its binding to the promoter region of NFAT5 gene, thereby activating NFAT5 expression and promoting melanoma cell proliferation, migration, and invasion." (PMID 39768127, 2024). "Other than that, ROR1, FOXC1, MIF, TGFβ, lncRNA SNHG17, MIAT, MHENCR, OR3A4 and H19 regulate proliferation, progression, migration, invasion, metastasis or EMT-like transition though PI3K/AKT pathway in melanoma cells." (PMID 32333246, 2020).
chronic lymphocytic leukemia (6 papers, 2016 to 2022). "Recent studies have reported that MIAT participates in chronic lymphocytic leukaemias progression and prostate cancer formation; however, the underlying mechanism of MIAT in tumorigenesis remains unclear." (PMID 29228680, 2017). "In summary, we showed that lncRNA MIAT is a potential new biomarker for aggressiveness of chronic lymphocytic leukemia and that MIAT functions to protect malignant mature B cells from cell apoptosis." (PMID 27527866, 2016). "MIAT is also a potential biomarker of chronic lymphocytic leukemia aggressiveness." (PMID 36620092, 2022). "The existence of such a regulatory feedback loop was further validated in aggressive chronic lymphocytic leukemia, where MIAT and OCT4 were found to increase survival and proliferation and suppress apoptotic cell death in malignant mature B cells and in cancer stem cell-like cells." (PMID 29914974, 2018). "Moreover, MIAT was found to be up-regulated in aggressive forms of chronic lymphocytic leukemia (CLL) and was suggested as a new biomarker for detecting the advance stages of CLL." (PMID 29914974, 2018). "MIAT had not been previously linked to EMT, but was shown to be upregulated in chronic lymphocytic leukemia and neuroendocrine prostate cancer." (PMID 29150601, 2017).
hepatocellular carcinoma (6 papers, 2019 to 2025). A malignant tumor that arises from hepatocytes. "It is worth noting that as an oncogene, MIAT can proliferate and migrate in various cancer cells such as hepatocellular carcinoma, osteosarcoma, and papillary thyroid carcinoma." (PMID 35299954, 2022). "In hepatoma cells, inhibition of miR-411-5p reversed MIAT knockdown-triggered suppression of STAT3 and PD-L1 expression, and regulation of the autophagy-related gene STAT3 by miR-411-5p may also be involved in the therapy of C. albicans infection with itraconazole and ritonavir." (PMID 40727105, 2025). "For instance, knockdown of miR-520d-3p promoted cell growth by inhibiting long non-coding RNA MIAT and EPHA2 expression in hepatocellular carcinoma." (PMID 34872448, 2021). "In hepatocellular carcinoma (HCC), MIAT was highly expressed in HCC tissues than normal tissues." (PMID 32274858, 2020).
osteosarcoma (6 papers, 2020 to 2023). A usually aggressive malignant bone-forming mesenchymal neoplasm, predominantly affecting adolescents and young adults. "We found that Bev treatment reduced the expression of MIAT in osteosarcoma cells as well as in the serum of osteosarcoma mice and serum-EVs." (PMID 35347106, 2022). "Further screening results showed 46 significantly differentially expressed lncRNAs, among which, MIAT was found to be significantly highly expressed in osteosarcoma samples." (PMID 35347106, 2022). "In consistency with our finding, it has been previously reported that MIAT was highly expressed in osteosarcoma tissues and silencing MIAT exercised an inhibitory effect on the progression of osteosarcoma." (PMID 33551826, 2020). "In osteosarcoma, MIAT occurred more frequently in cancerous tissues, and MIAT suppression significantly inhibited cancer cell proliferation." (PMID 32274858, 2020). "Subsequent RT-qPCR showed that MIAT was abundant in serum-EVs of osteosarcoma patients." (PMID 35347106, 2022). "Moreover, MIAT is significantly upregulated in both osteosarcoma tissues and cell lines, and this upregulation promotes malignant properties of osteosarcoma cells by enhancing VEGF-C." (PMID 35347106, 2022). "During the development of osteosarcoma, lncRNA myocardial infarction associated transcript (MIAT) has been identified to be upregulated in tumor tissues, while its knockdown leads to inhibition of osteosarcoma cell proliferation, which was achieved by binding to microRNA-613 (miR-613)." (PMID 35347106, 2022). "However, in clear cell renal cell carcinoma, the lncRNA myocardial infarction-associated transcript (MIAT) binds to and inhibits miR-29c action on LOXL2, while in osteosarcoma, the lncRNA human major histocompatibility complex p5 (HCP5) neutralises the action of miR-29b." (PMID 37762708, 2023).
ovarian carcinoma (6 papers, 2017 to 2024). A malignant neoplasm originating from the surface ovarian epithelium. "While the full implication of the lncRNAs MIAT rs1061540 and MALAT1 rs3200401 in ovarian cancer development remains to be determined, it is clear that MIAT rs1061540 played a role in modulating the risk of this disease in the present study cohort." (PMID 38390896, 2024). "In conclusion, our data provide novel evidence for a potential association between the lncRNA MIAT rs1061540 and the malignant condition of ovarian cancer, suggesting the involvement of such lncRNAs in OC development." (PMID 38390896, 2024). "Our comprehensive study identified three novel lncRNA (DNM3OS, MEG3, and MIAT) associated with ovarian cancer EMT." (PMID 29150601, 2017). "Reannotation of microarray probe sets showed that DIO3OS, DNM3OS, MIAT, and MEG3 lncRNA were detected in the two ovarian cancer subtypes at levels similar to known protein coding EMT-linked genes." (PMID 29150601, 2017). "Here we report an integrated analysis of >700 ovarian cancer molecular profiles, including genomic data sets, from four patient cohorts identifying lncRNA DNM3OS, MEG3, and MIAT overexpression and their reproducible gene regulation in ovarian cancer EMT." (PMID 29150601, 2017).